IL4 (interleukin 4)
Diseases named in the same sentence as IL4 in open-access papers (continued):
Sharing a sentence is not in itself a finding about the gene and the disease.
helminth infection (continued). "Nonetheless, helminth infections or their products induce a type 2 immune response, which produces cytokines, such as IL‐4, IL‐5 and IL‐13." (PMID 31496071, 2019). "Bystander consequences of this strong induction of IL-4 on memory CD8+ T cells is not well understood in the context of helminth infection that also drive strong regulatory responses." (PMID 30375396, 2018). "Here the authors show that IL4 production induced by helminth infection results in expansion of bystander CD8+ memory T cells and enhanced control to viral infection." (PMID 30375396, 2018). "Helminth infections are usually associated with Th2-type immune response characterized by the activation of CD4+ T helper cells and secretion of IL-4, IL-5, IL-9 and IL-13." (PMID 30189894, 2018). "Here, we have focused on B cell-derived IL-4, however, we cannot discount the involvement of other B cell-derived cytokines in driving development of Th2 immunity in response to helminth infections." (PMID 30619289, 2018). "Several groups reported differences in Th2 inflammatory responses in allergic lung inflammation and worm infection models using the IL-4 and IL-13 knockout and transgenic mice." (PMID 29868002, 2018). "Th2 cells secrete IL-4 to mediate humoral immunity and control helminthic infection via the production of IgE by B cells, which can activate antibody-dependent killing of eosinophils, macrophages and mast cells." (PMID 30400957, 2018). "Anti-inflammatory Th2 (T2) phenotype lymphocytes produce interleukin-4 (IL-4) and are responsible for the humoral immune response and prevention of helminth infections and response to allergen agents." (PMID 29875681, 2018). "Our data demonstrates that IL-4/IL-4Rα activated AAMφ orchestrate eosinophil immunity to filarial tissue helminth infection." (PMID 29547639, 2018). "Mice with a myeloid cell-specific knockout of IL-4 receptor-α (IL4Rα) were found to lack M2 macrophage development in mouse models of helminth infection and in Th2 cell-mediated inflammation, where IL-4 has a major role." (PMID 30546316, 2018). "IL4 secretion by Th2 and Tfh cells during helminth infection likely promotes LTβ expression by follicular B cells which then expands the stromal cell compartment to reorganize lymph node architecture." (PMID 30386324, 2018). "Certainly, helminth infections typically lead to an increased production of IL-10 and Th2 cytokines, such as IL-4, and to the down-regulation of Th1 cytokines." (PMID 30500849, 2018). "Although basophils are an important source of IL-4 and IL-13, they have been shown to be dispensable in the generation of the Th2 response in some helminth infections [e.g., during Nippostrongylus brasiliensis infection in basophil-deficient mice (Mcpt8-cre)]." (PMID 29670630, 2018). "By contrast, helminth infections typically direct the immune system toward a type 2 response, characterized by high levels of the cytokines IL-4 and IL-10, which can antagonize IFNγ production and its biological effects." (PMID 29312343, 2017). "In contrast, helminth infection-generated IL-4 induced, arginase (ARG-1) expressing alternative macrophage activation has been shown in murine systems to lead to impaired mycobacterial immunity." (PMID 28658262, 2017). "Chronic helminth infections (exposure to which occurs early in life in most endemic countries) lead to expansion of IL-4 mediated AAMs." (PMID 28658262, 2017). "In contrast, during helminth infection MΦ are activated by IL-4Rα-signaling and called M(IL-4), or ‘alternatively activated’." (PMID 28334040, 2017). "By contrast, helminth infections induce IL-4/IL-5 and IL-13 producing CD4 T cells and regulatory T cells associated with the alternative activation of macrophages for repair of tissues injured upon migration of worms across different body compartments." (PMID 28759590, 2017). "In contrast, under Th2 conditions (e.g., helminth infection or IL-4 administration), recruitment of blood-derived macrophages is scant." (PMID 28094319, 2017).
helminth infection (continued). "Remarkably, establishment of CAC significantly reduced the IL-4 response of CD4+ T cells after helminth infection which was accompanied by a prolonged survival of the worms." (PMID 28938014, 2017). "Our findings expand on this understanding by demonstrating that production of SP-D following helminth infection is significantly dependent on key protective immune responses against N. brasiliensis; namely IL-4/IL-13 signaling via IL-4Rα." (PMID 26900854, 2016). "Despite a good understanding of the inflammatory cascade elicited following helminth infection, the initial source of IL-4 is unclear." (PMID 26883724, 2016). "Here the authors show that activation of Type 2 immunity by helminth infection counteracts the development of inflammatory arthritis, a type 17-mediated pathology, via IL-4/IL-13- STAT6 signalling and eosinophil activation." (PMID 27273006, 2016). "During helminth infections, there is a predominant Th2 response characterized by a high production of IL-4, IL-5, IL-9, IL-10 and IL-13 cytokines." (PMID 27783986, 2016). "Recent work has demonstrated that tissue-resident macrophages can proliferate in situ during helminth infection through a process requiring the type 2 cytokine interleukin-4 (IL-4)." (PMID 27923070, 2016). "Overall, this study highlights a previously unrecognized and important role for ILC2-derived IL-4 for TH2 differentiation in a natural TH2-dependent model of human helminthiasis." (PMID 26883724, 2016). "The immune response of the host to helminths infection correlates with the production of interleukins (IL-4, 5, 9, 10, 13) and consequently the development of strong IgE response." (PMID 26187732, 2015). "This is due to the fact that, helminths infections are potent stimulators of IL-4 dependent synthesis of helminths specific IgE." (PMID 26187732, 2015). "Mice with selective deletion of IL-4/IL-13 in T cells (4-13Tko mice) are unable to mount a serum IgE response and show impaired GC formation after helminth infection." (PMID 26523376, 2015). "According to a recent study, Tfh cells serve as a alternative source of IL-4 in a helminth infection model." (PMID 26278622, 2015). "IL-4 is an instrumental component in protection against or the clearing of many helminth infections, with levels peaking soon following new parasite infections and falling a couple of months after infection attenuation." (PMID 25388877, 2014). "Recruitment of eosinophils to the site of helminth infection is greatly enhanced by the presence of AAMΦ 176 and recruitment of monocytes and neutrophils is discouraged by IL-4 9,19." (PMID 25319331, 2014). "The ligands of the IL13Rα1, IL13 and IL4, are components of type II immune responses, which characterize allergic reactions and helminth infections, and, interestingly, are also involved in the susceptibility of DA neurons to death by oxidative stress." (PMID 25525298, 2014). "Helminth infections, by their nature, lead to potent induction of Th2 responses (acutely) characterized by increased IL-4, IL-5, and IL-13 and—over time—to an expansion of Tregs." (PMID 24728010, 2014). "All helminth infections are characterized by the induction of antibody isotypes of the class – IgE and IgG4 (IgG1 in mice), that are largely dependent on the IL-4." (PMID 24498448, 2014). "Local proliferation has been noted in other worm infections, during which the immune response is Th2-like and IL-4 produced by Th2 cells promotes macrophages to become “alternatively (or M2) activated”." (PMID 25144366, 2014). "Even though they have common immunological features (elevated levels of IgE, eosinophilia, and production of Th2 cytokines such as IL-4 and IL-5), epidemiological studies revealed an inverse relationship between helminth infections and allergic diseases." (PMID 23844022, 2013). "During helminth infection, Tfh cells in reactive lymph nodes produced IL-4 while its deletion resulted in defective B-cell expansion and maturation." (PMID 24308005, 2013).
helminth infection (continued). "In chronic human and experimental infections, Schistosoma mansoni, like all helminth infections, induces a predominantly Th2 immune response, characterized by interleukin-4, IL-5, IL-9, IL-10 and IL-13, antibody (IgE and IgG4), eosinophils and mast cells." (PMID 23849678, 2013). "The immune response to chronic helminth infection is dominated by a self-reinforcing Th2 feedback loop between cytokines IL-4, IL-5, IL-13, and prominent expansion of eosinophils and mast cells." (PMID 24009607, 2013). "Further, helminth infections induce the production of Th2 related cytokines, such as IL-4, IL-5, IL-9 and IL-13, with anti-inflammatory qualities." (PMID 23782752, 2013). "Type 2 immune responses, characterized by the induction of cytokines IL-4, IL-5, the antibody isotypes IgG1 and IgE, as well as expanded populations of eosinophils, are induced by and confer protection against helminth infections in both humans and animals." (PMID 23844022, 2013). "The majority of IL-4-producing T cells in lymph nodes responding to helminth infection are follicular helper-T cells (T-fh), which are functionally distinct from TH2 cells." (PMID 22927819, 2012). "Previous studies on murine systems have shown that IL13 can complement IL4 or play an alternative or even stronger role in helminth infections." (PMID 22253585, 2012). "Conventional AAMΦ observed following helminthinfection are IL-4/IL-13-dependent, and analyses of the DEC mRNA transcript levelsdemonstrated that the AAMΦ-like population was absent in 4xIL-4Rα−/− mice." (PMID 21445234, 2011). "In vivo administration of antibodies or recombinant cytokines that raise IL4 levels diminish helminth infection; conversely, lowering IL4 levels increases helminth infection." (PMID 20649995, 2010). "More specifically, helminth infections tend to promote a type 2 bias in the immune response, involving the production of the cytokines interleukin-4 (IL-4), IL-5, IL-10, and IL-13, as well as immunoglobulin E." (PMID 17083720, 2006). "Viewing an interaction conversely, we found several Th2 cytokines known to be highly expressed during helminth infection such as IL-4, IL-5, and IL-10 to also be influenced by concomitant diabetes (i.e., they had high DDI interaction term contributions of 42.79%, 36.51%, and 55.52% respectively)." (PMID 41174472, 2025). "Helminth infections are well known to induce Th2 and regulatory immune polarization, characterized by increased IL-4, IL-5, IL-10, and IL-13 production and expansion of T regulatory cells, which suppress Th1/Th17 effector responses critical for antimycobacterial immunity." (PMID 41583474, 2025). "Indeed, IL-4 and IL-13 signaling via the type 2 receptors orchestrate type 2 immunity to helminth infections and can curtail chemotaxis and several effector functions of neutrophils in mice and humans, thereby mitigating detrimental tissue damage." (PMID 40586608, 2025). "Finally, the role of T cells during helminth infections has been widely reported, mainly due to its IL-4 production in a STAT6-dependent fashion, inducing the anti-inflammatory profile needed to generate protection." (PMID 38392907, 2024). "All support the well-established type 2 hypothesis in helminth infections, marked by an increase in Th2 type cytokines such as IL-4, IL-5, and IL-13 in mucosal tissue of the bladder in response to Sh eggs as well as systemically and in lymphoid tissue." (PMID 39250522, 2024). "Ym1 protein is expressed gene in helminth-activated macrophages and may be activated by helminth infection independently of IL4/IL13 signaling." (PMID 38511816, 2024). "To interrogate choline metabolism function in the physiologic setting of a Th2-skewed environment driven by helminth infection, we infected female mice with Heligmosomoides polygyrus (Hp), a parasitic nematode that colonizes the small intestine and drives protective M[IL-4]-like responses." (PMID 37747879, 2023).
helminth infection (continued). "Moreover, when choline uptake and metabolism was inhibited, we observed select but striking differences in metabolic and IL-4-specific responses, underpinned by a dramatic reduction in RELMα both in vitro and in mouse parasitic helminth infection." (PMID 37747879, 2023). "Alternatively, IL-4 and IL-10 present in the spleen during helminth infection may act directly on antigen-specific Th cell differentiation after immunization and block Th17 and Th1 bias." (PMID 36753434, 2023). "In combination with the fact that T cells are a robust source of Th2 cytokines after helminth infection, our findings imply that recipient T lymphocytes, stimulated to produce IL-4 and TGF-β after helminth infection, are the critical drivers of Th2-dependent regulation of GVHD." (PMID 37294277, 2023). "IL-4+ Tfh cells are involved in both helminth infections and allergic sensitization, but it was recently found that allergens drive the differentiation of another IL-4+ Tfh cell population, characterized by the co-expression of IL-4 and IL-13." (PMID 37372929, 2023). "Group 2 innate lymphoid cells (ILC2) are innate cells of lymphoid origin that develop from a common lymphoid progenitor and play pivotal roles in immune protection against helminth infection by secreting type 2 cytokines such as interleukin (IL)-4, IL-5, IL-9, and IL-13." (PMID 36109558, 2022). "Thus, several questions about the role of glycolysis during IL-4 polarization and helminth infection remain unanswered." (PMID 35154105, 2022). "In fact, protozoan could polarize macrophages toward an anti-inflammatory phenotype (similar to the one induced by IL4 during helminth infection) to escape the killing by macrophages and favor their replication." (PMID 35154105, 2022). "Helminth infection can alter Th1/Th2 immune polarization, reduce systemic levels of Th1/Th17 pro-inflammatory cytokines (IL-4 over IL-17, TNF-α and IFN-γ), switch macrophages from M1 to M2 pattern, or change intestinal microbial diversity, all of which lead to increased insulin sensitivity." (PMID 35639713, 2022). "Helminth infections typically induce a T-helper (Th) 2 immune response, with an immunoglobulin E antibody class switch, production and activation of eosinophils, mast cell degranulation, and marked elevation of interleukin 4, 5, and 13 (IL-4, IL-5, and IL-13)." (PMID 33104201, 2022). "Similarly, domestic sheep lines artificially selected to be more resistant to helminth infection showed enhanced IL-4 (Th2) responses." (PMID 35210503, 2022). "Additionally, MCs have been shown to secrete IL-4 and IL-13, however, the functional roles of mast cell-derived type 2 cytokines in trained immunity during allergy or helminth infection warrants further investigation." (PMID 36065058, 2022). "As IL-4 is an important macrophage proliferation/survival cytokine during helminth infection, LP diet may have reduced IL-4 production in the spleen, which has limited the macrophage proliferation and activation in the spleen." (PMID 35264261, 2022). "However, in response to helminthic infections, the type 2 immune response, specifically IL-4-dependent macrophage proliferation and activation, is required to promote repair of both the liver and lung." (PMID 34307393, 2021). "Compared to the RELMα-cre mice, or other studies in helminth infection, we found that peritoneal macrophages were the dominant source of RELMα, while eosinophils and B1 cells only expressed modest levels of RELMα in response to IL-4." (PMID 34349768, 2021). "Moreover, LPS, IL-4, or helminth infection induces KDM6B, leading to the modulation of macrophage activation 10-12." (PMID 34093857, 2021). "Furthermore, our results revealed that Adrb2−/− mice infected with C. sinensis showed significantly lower production of type 2 cytokines, in particular, IL-4 (P<0.001) and IL-13 (P<0.01), compared to that observance in Adrb2+/+ mice with worm infection." (PMID 34733286, 2021).
helminth infection (continued). "However, we did not observe any differences in Th2 cell polarization, potentially because we interrogated the effect of RELMα on IL-4-induced responses, compared to the more complex outcomes and regulatory networks in helminth infection." (PMID 34349768, 2021). "Although it is clear that smooth muscle cells respond to IL-4/IL-13 in helminth infections, whether this influences the outcome in ulcerative colitis has not been studied." (PMID 32410852, 2020). "These might be related to the fact that Tfh cells are the primary IL-4-producing cells during helminth infection." (PMID 32197642, 2020). "Alterations in intestinal mucus production and glycosylation are known to occur during gastrointestinal helminth infections and, given the essential role of the IL-4/IL-13 pathway in goblet cell hyperplasia, mucus secretion and glycosylation, are likely to arise during intestinal schistosomiasis." (PMID 33329584, 2020). "Helminth infections are a global health burden in humans and livestock and are considered to be a major evolutionary driver of type 2 immunity (orchestrated by type 2 cytokines, e.g., IL‐4 and IL‐13)." (PMID 31267552, 2019). "Furthermore, IL-4-activated macrophages help to control helminth infections and induce tissue repair." (PMID 31178861, 2019). "Additionally, CL patients with a concomitant helminth infection, known to drive a polarized Th2 response characterized by high IL-4 levels, bear lesions that take longer to heal as compared with helminth-free patients." (PMID 31637219, 2019). "However, as shown for helminth infections and in anti-tumor responses, Irf4−/− mice showed hampered M2 macrophage polarization, when stimulated with IL-4 and IL-13 ex vivo." (PMID 31632388, 2019). "In helminth infections, alternatively activated macrophages (M2), whose activation occurs mainly via the IL-4/STAT6 pathway, have a major role in mediating protection against excessive inflammation, and has been associated with both tissue repair and parasite clearance." (PMID 31810203, 2019). "The role of IL-4 under physiological conditions is to enhance the antibody response by promoting the survival and proliferation of B cells and provide defense against helminth infection." (PMID 30174703, 2018). "Also, oral helminth infections can control type 1 diabetes through mechanisms that involve both CD4 T cell production of IL-4 and IL-10 acting in an independent and redundant manner." (PMID 30386324, 2018). "While IL-4 has been correlated with a protective effect during fungal reinfection, IL-13 is known to promote intestinal goblet cell hyperplasia and increased mucin expression during parasitic helminth infections." (PMID 30555491, 2018). "Thus, during helminth infection IL-4 can expand and condition TVM cells for more rapid CD8 responses against subsequent cognate Ag encounter." (PMID 30375396, 2018). "Although these papers described the differential production of and dependence on IL-4 and IL-13 in many of the phenotypic endpoints of Th2-mediated inflammation to allergen challenge or worm infection, few if any described the upstream signaling differences elicited by the two cytokines." (PMID 29868002, 2018). "Helminth infection may activate adipocyte precursors to adopt a beige fate through induction of the cytokines IL-4/IL-13 and ILC2s9, as these Th2 promoting molecules and cells have been implicated in the commitment and maturation of beige adipocytes." (PMID 29545532, 2018). "Type 2 immune response, featured by elevation of IL-4 and IL-13 levels, plays a crucial role in host protection as well as pathological tissue fibrosis after helminth infection, including schistosome infection, but the signals that induce type 2 immunity are poorly understood." (PMID 29554131, 2018).